TLR9 (toll like receptor 9)
Diseases named in the same sentence as TLR9 in open-access papers (continued):
Sharing a sentence is not in itself a finding about the gene and the disease.
tumor (continued). "In addition, the CpG-ODNs inhibited proliferation and induced apoptosis of TLR9-positive tumor cell lines in vitro." (PMID 23561041, 2013). "The immunomodulatory effects of the combination therapy improved local control of RT and reduced systemic pulomonary metastases, thus providing a strong rationale for combining RT with TLR9 agonist immunotherapy for improved loco-regional and systemic tumor therapy." (PMID 22666458, 2012). "Moreover, the expression of TLR9 was also reversely correlated with the expression level of Ches1 in the tumor tissues (p<0.05)." (PMID 23133627, 2012). "Next we analyzed whether RT could facilitate the infiltration of TLR9 agonist-activated NKDCs in the irradiated tumor tissues." (PMID 22666458, 2012). "It is possible that primary tumor RT effectively generates a local tumor antigen pool for APCs, such as, TLR9 agonist-activated pDCs, which then uptake the tumor antigens and migrates to the lymph nodes where it stimulates the Th2 cells to elicit a humoral immune response." (PMID 22666458, 2012). "Since NKDCs were reported as a potent effect cell population that has direct cytotoxic effect against tumor cells, these results indicate NKDCs might contribute to the anti-tumor effects, induced by combined TLR9 agonist and RT treatment." (PMID 22666458, 2012). "However, the possible effect of miRNA-574-5p on the enhanced tumor progression induced by TLR9 signaling still remains to be elucidated." (PMID 23133627, 2012). "To investigate the mechanism of TLR9 agonist+RT induced anti-tumor effect in these mice, we first examined whether tumor-specific T cell immune response is induced by IFN-γ ELISPOT assay." (PMID 22666458, 2012). "Notably, we found that down-regulation of miRNA-574-5p using miR-574-5p inhibitor in vitro or miR-574-5p sponge in vivo significantly abrogated the enhanced tumor progression induced by TLR9 signaling." (PMID 23133627, 2012). "Combined RT with TLR9 agonist treatment inhibited 3LL tumor growth in both wild type and B−/− mice." (PMID 22666458, 2012). "Our findings suggested that miR-574-5p was an important player in TLR9 signaling and tumor biology." (PMID 23133627, 2012). "TLR9 agonists also enhance the differentiation of B cells into antibody-secreting plasma cells and could potentially eradicate tumor cells through antibody dependent cellular cytotoxicity (ADCC)." (PMID 22666458, 2012). "Importantly, we found that the expression level of miR-574-5p was positively correlated to the expression of TLR9 in clinical tumor tissues (p<0.05)." (PMID 23133627, 2012). "Since anti-tumoral IgG titers were induced after RT+TLR9 agonist treatment, we next examined whether these auto-antibodies were bound to the irradiated tumor tissue in situ." (PMID 22666458, 2012). "Notably, we identified checkpoint suppressor 1 (Ches1) as the dominant direct target for miRNA-574-5p to confer the TLR9 signaling enhanced tumor progression." (PMID 23133627, 2012). "We next determined whether combination treatment of RT+TLR9 agonist induces a systemic tumor-specific immune response in vivo." (PMID 22666458, 2012). "In addition to immunoexpression of TLR9 in the tumour cells, immunoreactivity was observed in endothelial and inflammatory cells as well as in some fibroblasts." (PMID 21929816, 2011). "There were 138 RCC tumours available for the evaluation of TLR9 immunoreactivity." (PMID 21929816, 2011). "Some nuclear TLR9 immunopositivity was also detected in 60 (44%) tumour samples." (PMID 21929816, 2011). "Of the studied tumours, 112 (81%) exhibited cytoplasmic TLR9 immunostaining." (PMID 21929816, 2011). "We think CpG ODN may activate TLR9 and promote tumor progression if it was delivered locally into the tumor within the brain." (PMID 20696081, 2010). "After binding with the ligand, TLR9 signal pathway may induce the proinflammatory or progrowth microenvironment of tumor." (PMID 20696081, 2010).
tumor (continued). "Indeed, it was demonstrated that stimulation of TLR-9 activates human plasmacytoid dendritic cells and B cells, thus inducing potent innate immune responses in preclinical tumor models as well as in patients." (PMID 21129170, 2010). "Accumulating data indicated that TLR9 agonist CpG ODN can promote tumor development and metastasis." (PMID 20696081, 2010). "IRF-5 is a key player of TLR7/TLR9 signalling and is involved in tumor cell growth and apoptosis." (PMID 19430534, 2009). "Taken together, these findings suggest that the combination of CP-870,893 and CpG ODN 2006 represents a practical - and available - clinical approach to test the hypothesis that dual CD40/TLR9 activation in vivo can promote tumor immunity in patients." (PMID 19906293, 2009). "The expression of TLR9 in tumor cells and cell lines rises up the question, whether this receptor is functional active in these cells." (PMID 15631627, 2005). "We determined whether a direct interaction of bacterial DNA with the tumor cells themselves is possible and investigated the expression and function of TLR9 in human malignant solid tumors and cell lines." (PMID 15631627, 2005). "Summarized results of immunohistochemistry (IHC) targeting TLR9 in tumor tissues and cell lines." (PMID 15631627, 2005). "To confirm the results obtained by ISH we analyzed TLR9-transcripts in tumor cell lines by RT-PCR." (PMID 15631627, 2005). "To gain insights into whether TLR9/BCR coactivation causes similar remodeling in primary B cells and in MCD DLBCL, we cross-compared proteomes from αIgM/CpG-stimulated primary B cells or the tumor-derived MCD DLBCL HBL1 cell line with resting primary B cells." (PMID 40924473, 2025). "Because GET introduces DNA into both the cytosol and endosomes of the cell, we wondered whether the observed inflammation results from activation of the well-established endosomal PRR TLR9 or from the more recently identified cytosolic DNA sensors in tumour cells." (PMID 41401059, 2025). "Since TLR9 plays a crucial role in the innate immune system through the recognition of microbial infection, high protein expression could reflect microenvironmental activation against microbial DNA in tumor cells." (PMID 40437466, 2025). "On the other hand, TLR9 upregulation may facilitate tumor progression and metastasis." (PMID 39123407, 2024). "Indeed, TLR9 engagement by intralesional administration of CpG ODN nanorings gave promising results in a thymoma mouse model, where the increased production of IFN-α by pDCs associated to reduced tumor size and volume." (PMID 38504978, 2024). "However, the functional activity of TLR9 in tumor cells should be further investigated." (PMID 39020402, 2024). "Therefore, PDGF-DD stimulation could enhance IFN-α secretion induced by the TLR9-mediated pDC response to self-DNA released by necrotic tumor cells." (PMID 39020402, 2024). "To gain insights into whether TLR9/BCR co-activation causes similar remodeling in primary B-cells and in MCD DLBCL, we cross-compared proteomes from aIgM/CpG-stimulated primary B-cells or the tumor-derived MCD DLBCL HBL1 cell line with resting primary B-cells." (PMID 38854072, 2024). "In particular, the expression values of TLR-2, TLR-3, TLR-4, and TLR-9 on CD3-CD56+ cells increased proportionally with the tumor stage, suggesting that these receptors may be functional as diagnostic and prognostic biomarkers in assessing the progression of GC." (PMID 39594809, 2024). "In MM, it was shown that a TLR9 agonist could restore the ability of patient-derived plasmacytoid dendritic cells (pDCs) to stimulate T-cell proliferation and that activating TLR9 in a xenograft MM model reduced tumor load." (PMID 38911853, 2024).
tumor (continued). "This hypothesis gains support from recent discoveries in cancer research, wherein intra-tumoral injection of cytokines or TLR9 agonists has demonstrated substantially greater effects on tumor size and tumor-specific immune responses compared to the same therapies administered s.c. or i.v.48,49." (PMID 37696935, 2023). "However, TLR9 can also promote tumor progression and enhance the invasiveness of cervical tissue." (PMID 36365103, 2022). "Notably, while TLR9 expression remains modest, it is up-regulated in all 33 tumours." (PMID 35801728, 2022). "Meanwhile, the inhibitor of TLR9 which was a receptor of NETosis could retard tumor progression." (PMID 34758877, 2021). "Among them, the TLR9 agonist showed improved therapeutic effects, whether used alone or in combination with other drugs, immunocheckpoint blocking therapy, or as an adjuvant of a tumour vaccine." (PMID 33407720, 2021). "However, TLR9 has also been shown to exhibit a tumor-promoting activity." (PMID 34573939, 2021). "The addition of low-dose CpGODNs targeting TLR9 to a vaccine based on immune stimulatory complexes (ISCOM) inhibited the tumor immune evasion in an orthotopic model of pancreatic carcinoma inducing an effective CTL-mediated tumor cell killing and prolonging mice survival." (PMID 34884547, 2021). "When TLR-9 agonist CpG was delivered by OND, the number of T, B, conventional DCs (cDCs) and pDCs in the LN increased at least threefold higher than that delivered by PPS NP, thus OND resulted in a nearly complete loss of LN EL4 tumor burden and a reduction of the size of the primary EL4 tumor." (PMID 34823541, 2021). "In addition, several preclinical studies have demonstrated that agonists of the TLRs (TLR3, TLR7/8 and TLR9) in macrophages may enhance anti-tumor treatment efficacy by polarizing M0 macrophages into Th1 and M1-like TAMs and inhibiting tumor progression." (PMID 33323552, 2020). "Therefore, understanding the effects of TLR9 in tumor cells on antitumor immunity may lead to the discovery of new therapeutic targets for cancer therapy." (PMID 32483468, 2020). "In a Panc02 model expressing ovalbumin, the combination of a vaccine based on immune stimulatory complexes (ISCOM) and a TLR9 agonist could restore anti-tumor immune response by activating NK cells, cytotoxic T cells, and dendritic cells, leading to tumor regression." (PMID 32961746, 2020). "In addition, we also demonstrated that lipoE7m combined with PSCpG could synergistically trigger the TLR2 and TLR9 pathways to decrease tumor immunosuppressive cells, including Tregs and MDSCs, to enhance the therapeutic effect of lipoimmunogens." (PMID 32231003, 2020). "In our previous study, a TLR2 agonist recombinant lipoprotein combined with the TLR9 agonist CpG oligonucleotide (CpG ODN) could dramatically enhance antitumor efficacy and reduce the number of tumor-associated macrophages (TAMs) and myeloid-derived suppressor cells (MDSCs)." (PMID 32231003, 2020). "Thus, we questioned whether generating a potent T cell product could be achieved by simply culturing anti-tumor T cells ex vivo with TLR9 agonist, CpG." (PMID 30400835, 2018). "The TLR9-mediated activation of the NF-κB signalling pathway and the associated enhanced expression of matrix metalloproteinase-2 (MMP-2), MMP-7 and cyclo-oxygenase 2 mRNA, all factors associated with tumour progression and migration, can explain the role of TLR9 in cancer." (PMID 29225688, 2017). "Therefore, TLR9 agonists could perform its therapeutic potentiality on B-cell malignancies through the host immune cells and/or direct effects on the tumor cells." (PMID 28241765, 2017). "Regarding pathway assignments of at least 20 HRO tumours, 10 top-ranked genes, of which 9 were lost in 3p, were linked with 7 to 45 pathways (n = 280) comprising RAF1 (45 PWs), RHOA (25 PWs), IPTR1 (22 PWs), CACNA1D, ITGA9 (8PWs), WNT7A (8 PWs) TLR9 (7PWS9, LAMB2 (7 PWs) and ARPC4 (6 PWs)." (PMID 28486536, 2017).
tumor (continued). "In another patient, a TLR9 mutation was detected in Barrett’s but not the adjacent tumor." (PMID 28531216, 2017). "Taken together, nano-particulate TLR9 agonist injected intravenously can scout out tumor microenvironment to provoke local innate immune activation and release dead tumor cells into circulation that may induce broader and protective tumor antigen-specific CD8 T cells." (PMID 27384490, 2016). "Therefore, expansion of cancer stem cell population could result from TLR9-mediated response to environmental conditions, thereby limiting the outcome of cytotoxic tumor therapies." (PMID 26046794, 2015). "Indeed, TLR-9 agonists were shown to induce the recruitment of immune effector cells through the activation of pDCs and the consequent copious release of cytokines and to inhibit MDSCs richly present around tumor mass." (PMID 28548068, 2014). "Solid preclinical evidence had been provided to support multiple mechanisms of action for TLR-9 agonists, either on tumor, endothelial and immune cells, suggesting that this class of agent may play an anti-tumor role, both directly on cancer cells and indirectly on the tumor microenvironment." (PMID 28548068, 2014). "Interestingly, addition of primary tumor RT caused minimal changes in the phenotype of splenocytes suggesting that RT does not suppress the immunomodulatory effects of TLR9 agonist." (PMID 22666458, 2012). "The immunoexpression of TLR9 did not associate with tumour necrosis (data not shown)." (PMID 21929816, 2011). "Thus, the contribution of either high or low TLR9 expression to the pathophysiology of cancer may be highly tumour specific." (PMID 21929816, 2011). "Thus, TLR7 or TLR9 agonists may promote anti-tumor activity directly or via other immune mechanisms." (PMID 18652679, 2008). "Secondly the upregulation of TLR9 could be beneficial to the tumor, promoting tumor cell survival." (PMID 15631627, 2005). "Our findings show that MGNs simultaneously track CD8+ T cells and VEGFR2+ expressing tumor cells in 4T1 tumors in vivo with multiplexed SERS imaging, enabling us to predict treatment response to STING + TLR9 immunotherapy." (PMID 41543356, 2026). "Elevated expression of TLR1, TLR2, TLR4, TLR5, TLR6, and TLR9 has been detected in GBM, particularly within the mesenchymal subtype with significant impact in tumor progression." (PMID 41157253, 2025). "It has been demonstrated that mitophagy-released mtDNAs activate cancer stem-like cells (CSCs) via the TLR9-Notch1-AMPK axis, leading to chemoresistance and tumor recurrence." (PMID 41293166, 2025). "We also compared the antitumor effects of SUP3 with other TLR agonists in B16F10 tumor-bearing mice treated with the TLR3 agonist PolyI: C and the TLR9 agonist CpG-ODN." (PMID 41291775, 2025). "Toll-like receptor 9 (TLR9), another key player in immune evasion, upregulates PD-L1 and promotes tumor growth through the PARP1/STAT3 pathway, enhancing tumor cell proliferation, migration, and invasion." (PMID 40486875, 2025). "The TLR-9 agonist 1018 ISS, when combined with rituximab, significantly increased CD8+ T cell and macrophage infiltration in tumor tissues." (PMID 41200171, 2025). "The TLR9 (toll-like receptor) activates PRR pathways, stimulating tumor-resident innate immune cells like dendritic cells." (PMID 40647424, 2025). "Showed that radiotherapy combined with a TLR9 agonist enhances CD8 + T cell activation and delays tumour growth." (PMID 41123840, 2025). "Approaches such as modifying the tumor microenvironment through anti-TGF-β or anti-CD73 antibodies, activating innate immunity with TLR9 agonists, or employing combination regimens involving checkpoint inhibitors and targeted therapies show potential." (PMID 40647424, 2025). "In previously reported models of surgery-accelerated tumor growth, poly(I:C), a known TLR3 agonist, and CpG-DNA, a known TLR9 agonist, have both demonstrated efficacy." (PMID 41208108, 2025).
tumor (continued). "As discussed in Section 2 and Section 3, receptors such as TLR2, TLR4, TLR7, TLR9 and NLRP3 generally promote tumor progression and immune suppression." (PMID 41157253, 2025). "TLR9 promotes the expression of PD‐L1 by regulating STAT3 signaling and enabling tumor cells to escape immune surveillance." (PMID 40727252, 2025). "TLR9 seems to play a dual role in the pathogenesis of GBM, both as an immune factor eliminating the tumour and as a pro-tumoural molecule." (PMID 38247816, 2024). "The dual role of TLR9 and TLR7 in cancer is complex and their effects can be context-dependent, depending on various factors, including the specific type of cancer and tumor stage." (PMID 38850110, 2024). "TLR-9 increased HCC cells proliferation, tumor growth, oxidative markers, and autophagosome formation." (PMID 38398197, 2024). "TLR9 is upregulated in human OSCC in vitro and in vivo, and its high expression correlates with advanced tumor stage and decreased survival rates." (PMID 38850110, 2024). "Furthermore, unlike other immunotherapies, such as immune checkpoint inhibitors that aim to reverse the exhaustion state of T cells, TLR9 agonist combined with RT causes activated CD8+ T cells that are not yet exhausted to infiltrate the tumor and enhance the radiation response." (PMID 39133651, 2024). "Activation of plasmacytoid dendritic cells (pDCs); induction of CD8+ T cell responses via TLR9 in a CD4+ T cell-independent manner; remission of tumor." (PMID 38983849, 2024). "Tumor-derived PGE2 and TGF-β were shown to act in synergy to inhibit the production of IFN-α and TNF-α induced in TLR7- and TLR9-triggered pDCs, by decreasing TLR membrane expression or by blocking TLR downstream signaling." (PMID 38504978, 2024). "In contrast, tumor cells often exhibit overexpression of specific TLRs, such as TLR2, TLR4, and TLR9." (PMID 39640496, 2024). "In other types of gynecologic cancers, TLR9 pathway activates lymphocyte T cell shift towards Th1 profile and decreases the number of MDSCs, TAMs and Tregs in the TME, displaying anti-tumor properties." (PMID 38397187, 2024). "CpG-STAT3ASO disrupts tumour-induced immunosuppression by inhibiting activity of STAT3 and stimulating TLR9 signaling in antigen presenting cells, such as DCs ang macrophages." (PMID 38259453, 2023). "We also discovered a novel function and mechanism of TLR9 activation, which increased PS exposure on cancer cells, thereby attracting more BPRDP056 to the tumor site for cancer cell killing." (PMID 37324949, 2023). "As a Toll-like receptor 9 (TLR9) agonist, the antigenic peptide CpG-ODN is widely used in cancer immunotherapy to stimulate an effective immune response against tumours." (PMID 37375846, 2023). "The correlations established between TLR-9 expression and clinicopathological variables, including histological grade, tumor–node–metastasis (TNM) stage, and EBV presence, underscore the complexity of TLR-9’s engagement in GC development." (PMID 37894471, 2023). "Out of 21 ICD-related genes with notably different expressions, seven genes, namely ROCK1, BCL2, TLR2, TLR9, AGER, CASR, and P2RX7, were found to have decreased expression in tumor samples, while the rest were upregulated." (PMID 37932362, 2023). "In a study conducted by Jiang, TLR9 was found to be directly upregulated by freshly formed NETs, leading to stimulation of the NFκB, MAPK, and STAT3 pathways in tumor cells." (PMID 37365190, 2023). "The tumor-bearing mice underwent a therapy combining intratumoral CpG-oligodeoxynucleotides (ODN), a ligand of Toll-like receptor 9 (TLR9), and inhibitory interleukin-10 (IL-10) receptor antibodies (anti-IL-10R)." (PMID 37361202, 2023). "This suggests an alternative mechanism of tumor clearing induced by CDNP-R848 treatment and is in line with previous findings in a PDAC model after TLR9-targeted therapy." (PMID 36774352, 2023).